HMGB1 (high mobility group box 1)
Diseases named in the same sentence as HMGB1 in open-access papers (continued):
Sharing a sentence is not in itself a finding about the gene and the disease.
cancer (continued). "Cancer genome databases and paired-GB patient samples with or without TMZ treatment were used to assess the relationship between HMGB1 mRNA levels and overall patient survival." (PMID 35193644, 2022). "Additional evidence showed that the GPX4 inhibitor RSL3 induced early ferroptotic cancer cells was ICD and was accompanied by the production of DAMPs, such as purine adenosine triphosphate (ATP) and HMGB1." (PMID 36158661, 2022). "HMGB1 induces autophagy in the nucleus upregulating the expression of heat shock protein (HSP) 27, while in the extracellular space, once released by cancer cells, it binds RAGE inducing in turn autophagocytic activity in nearby cells." (PMID 36012593, 2022). "The most common studied DAMPs were Calreticulin, HMGB1, ATP, and Heat Shock Proteins (HSP) 70 and 90, which were either expressed on the cancer cells or released." (PMID 36135095, 2022). "The majority of anti-cancer agents and inducers of apoptosis and ICD such as doxorubicin, cardiac glycosides, septacidin, and Coxsackievirus B3, promote HMGB1 release." (PMID 36145510, 2022). "There are numerous experiments showing that HMGB1 executes the function that is widely engaged in dynamic interactions with other cells to remodel the TME, influencing cancer progression." (PMID 35637945, 2022). "Anthracyclines, e.g., doxorubicin or mitoxantrone, affect cancer cells by enhancing the cell surface expression of calreticulin (CRT) followed by the release of high-mobility group box 1 (HMGB1), ATP, annexin A1, and type I interferon from cancer cells." (PMID 36679904, 2022). "It is well established that DAMPs including HMGB1, heat shock protein (HSP), and antigens released via immunogenic cell death can activate the immune system against specific cancer cells." (PMID 35372046, 2022). "CiRS-7/miR-7/EGFR, circ_0067934/PI3K/AKT, circ_0067934/miR-1301-3p/HMGB1, and circ_0062389/miR-1179/HMGB1 regulate the EMT process and thus cancer tissue invasion/metastasis." (PMID 36230649, 2022). "Immunostimulatory danger-associated molecular patterns (DAMPs) (such as ANXA1, CALR, and HMGB1) and cytokines (such as IFN and CXCL10) were used to evaluate the immunogenicity of cancer cell death." (PMID 36003383, 2022). "In this study, OTUD6B expression has been unraveled to be positively correlated with most of the 47 immune checkpoint genes in almost all cancers, such as CD276, VEGFA, HMGB1, and TLR4." (PMID 36052059, 2022). "For single immune checkpoint gene, the immune stimulator HMGB1 correlated positively with KIF11 in all human cancer types, and TNFSF4, BTN3A1, BTN3A2, and ENTPD1 correlated positively with KIF11 in most human cancer types." (PMID 36742345, 2022). "HMGB1 was also investigated as a biomarker response for Boron neutron capture therapy (BNCT), a non-invasive therapeutic technique for treating malignant tumors but, as a newly developed technique, results are too scarce to make any final considerations." (PMID 36012593, 2022). "Low-dose lipotecan not only damages cancer cells but also triggers ER stress for CRT surface exposure and HMGB1 and ANXA1 release, regarded as the characteristics of ICD induction." (PMID 33799527, 2021). "Accumulating evidence has suggested the importance of the interactions of RAGE and RAGE ligands, such as HMGB1, S100s, AGE, and Aβ, in the pathogenesis of various human diseases, including cancer." (PMID 33805209, 2021). "GPR30-induced HMGB1 upregulation triggered MEK/ERK signaling, leading to increased autophagic behavior to protect cancer cells from TAM-induced apoptosis, mimicking the recombinant HMGB1-mediated increase in cancer cell resistance potential to TAM." (PMID 34182538, 2021). "Several ligands activate RAGE, i.e., advanced glycation end-products (AGEs) or high-mobility group box 1 (HMGB1) and contribute to cancer progression." (PMID 33922995, 2021). "Major determinants of immunogenicity and ICD include the release of HMGB1 and surface exposure of CRT from dying cancer cells." (PMID 34711820, 2021).
cancer (continued). "During ICD, annexin A1 guides antigen-presenting cells to dying cancer cells while HSP70, HSP90, HMGB1 and other molecules promote uptake and cancer antigen presentation to T cells." (PMID 34579759, 2021). "Recently, papaverine was revealed to suppress the HMGB1-RAGE inflammatory signaling pathway and cancer cell proliferation." (PMID 33805209, 2021). "Here we report that the involvement of HMGB1 in anti-cancer immune evasion is determined by Toll-like receptor (TLR) 4, which recognises HMGB1 as a ligand." (PMID 34234778, 2021). "It has been found that GSDME-mediated pyroptosis induced cancer cells proliferation and PCNA(proliferating cell nuclear antigen) expression through the ERK1/2 pathway by releasing intracellular HMGB1, which in turn promoted the development of CAC." (PMID 34381721, 2021). "From the viewpoint of the cancer immunity cycle, the synergy of the antitumor effects of PDT combination therapy, inducing CRT and HMGB1, and of checkpoint blockade cancer immunotherapy, using PD-1/PD-L1 antibodies, is strongly expected." (PMID 33670714, 2021). "Reportedly, HMGB1 can promote the invasion of NSCLC cells by activating PI3K/Akt and NF-κB pathways to produce MMP-9; in metastatic pancreatic ductal adenocarcinoma, HMGB1 promotes EMT and invasion of cancer cells by acting on RAGE/NF-κB axis." (PMID 33926347, 2021). "We have previously reported interactome studies of HMGB1 and HMGB2 proteins in prostate and ovary cancer cells based on the yeast two-hybrid approach, but the number of proteins identified was low." (PMID 34572914, 2021). "Major DAMPs are ATP, calreticulin (CALR), high-mobility group box 1 (HMGB-1), type I interferon (IFN), annexin A1 (ANXA1), heat shock proteins 70 and 90 (HSP70, HSP90), or diverse nucleic acids, mainly cancer cell derived ones." (PMID 33947098, 2021). "Secreted HMGB1 (ecto-HMGB1) and ANXA1 (ecto-ANXA1) were significantly detected at low doses of lipotecan in SW480 and CT26 cancer cell lines." (PMID 33799527, 2021). "We also confirmed that a vaccine effect results from injecting cancer cells with G-chlorin PDT and that this vaccine effect is cancelled by silencing CRT and HMGB1 with small-interfering RNAs." (PMID 33670714, 2021). "There appears to be a mechanism linking HMGB1 to immunosuppression and myeloid cells including TAMs and CD33-positive myeloid cells in patients with malignant tumors, which needs further studies to uncover." (PMID 34257571, 2021). "Our results reveal three important genes, HMGB1, APEX1, and POLE3, that function in the epigenetic control of a DNA-repair mechanism, which modulates cancer in HT29 cells, and induce apoptosis." (PMID 34500845, 2021). "TLR4 is one of the cell surface receptors of HMGB1, and TLR4/NF-κB pathway is reported to be responsible for cancer metastasis." (PMID 34552063, 2021). "PDT promotes dendritic cells’ phagocytic uptake of dying cancer cells by upregulating CRT and HMGB1." (PMID 33670714, 2021). "The most important DAMPs released from cancer cells during ICD are calreticulin, adenosine triphosphate (ATP), heat-shock proteins, and high mobility group protein B1 (HMGB1)." (PMID 33915703, 2021). "Spheroids were collected to evaluate the cancer stem cells (CSCs) markers, such as EPCAM, CD133, and CD24, in HMGB1/RICTOR manipulated cells using real-time PCR methods." (PMID 34916485, 2021). "A major endogenous TLR4 agonist, that is relevant to cancer, is the DAMP high-mobility group box 1 (HMGB1), which possesses protumour characteristics through sustaining an anti-inflammatory environment and promoting invasion metastasis and angiogenesis." (PMID 34771442, 2021). "Extra HMGB1 binds with high affinity to several receptors including TLR-2, TLR-4, and RAGE on endothelial, smooth muscle and cancer cells and neutrophils." (PMID 34199060, 2021). "In this work we discovered that in cancer cells expressing TLR4, HMGB1 can induce TGF-β production and secretion." (PMID 34234778, 2021).
cancer (continued). "During cell death, CT26 cancer cells treated with both AuNSw and laser expressed biomarkers for ICD such as high mobility group box 1 (HMGB1) and 70 kilodalton heat shock proteins (Hsp70)." (PMID 34641524, 2021). "The well-studied members in this subfamily, including HMGB1 and HMGB2, exhibited important functions in various cancer progression." (PMID 33842327, 2021). "The interaction of HmgB1 with TLR2 or TLR4 regulates inflammation process when lungs or liver are damaged due to epilepsy, heart disease, or cancer." (PMID 33114717, 2020). "Compared with the cancer clusters, the CSC cluster was highly differentially expressed with genes HMGB1, H2AFZ, KIAA0101 at p-value <1e-10, which was verified by CSC-related specific genes in previous studies." (PMID 33162821, 2020). "Specifically, Vascular Endothelial Growth Factor (VEGF), Transforming Growth Factor-β1 (TGF-β1), High Mobility Group Box-1 (HMGB1), glutamine, and glutaminase are reported to be mediators of the platelet-driven malignant progression of cancer." (PMID 32121098, 2020). "One of them is VEGF that overexpressed due to the increased level of HMGB1 in human oral squamous cell carcinoma (OSCC) and bladder carcinoma, facilitating angiogenesis of cancer and its proliferation." (PMID 32443845, 2020). "HMGB1 is a nuclear protein that can also act as a redox sensitive DAMP once released in the extracellular space by immune activated, necrotic, and cancer cells." (PMID 33072091, 2020). "DAMPs such as surface-exposed calreticulin, which secrete ATP and passively release high-mobility group protein B1 (HMGB1), are vital for the immunogenic cell death of cancer cells." (PMID 33297519, 2020). "Cytoplasmic HMGB1 is a BECN-1 binding protein, which forms autophagosomes via poly-ADP-ribosylation by PARP-1 in cancer cells, which in turn contribute to reduced drug sensitivity through autophagy upregulation." (PMID 33158052, 2020). "HMGB1 upregulated PI3K/Akt, which subsequently regulated various cellular proteins that induced cell proliferation and decreased apoptosis of cancer cells." (PMID 32443845, 2020). "Dendritic cells are activated by HMGB-1, and we assume that the density of HMGB-1 is proportional to the density of cancer cells." (PMID 32310956, 2020). "As PIT induces ICD, a mode of death where dying cancer cells release DAMPs, we next analysed major endogenous danger molecules: CRT, ATP, HSP70/90, and HMGB1." (PMID 33082328, 2020). "ICD features the spatiotemporally defined release of DAMPs (such as ATP and HMGB1), a type I IFN response, and the production of pathogen response-like chemokines that together enhance the immunogenic potential of dying cancer cells." (PMID 32778143, 2020). "At the pre-apoptotic stage, cancer exposed to ICD inducers not only transfers CRT to the outer leaflet plasma membrane and secretes ATP, but also releases the nuclear HMGB1 protein, which becomes permeabilized in the secondary necrosis." (PMID 34138119, 2020). "However, other studies have indicated that the HMGB1 SNPs are associated with a lower risk of cancer and a less invasive disease, or may even not be associated with the risk of cancer." (PMID 33023053, 2020). "We observed that High mobility group box 1 protein (HMGB1) was highly expressed in human TNBC and positively correlated with cancer metastasis." (PMID 32943604, 2020). "Dying cancer cells induced by PS-PDT or PD-PDT emit calreticulin, HMGB1 and ATP and they were efficiently engulfed by BMDCs, which then matured, became activated and produced IL-6." (PMID 31842994, 2019). "Here, we tested the hallmarks of ICD in IR-780 treated cancer cells and observed dose-dependent increases in ATP and HMGB1 secretion, as well as the expression of the ER/cytosolic chaperone, CRT, on the surface of cancer cells." (PMID 31781498, 2019). "HMGB1 is a ligand for RAGE that is highly expressed in various cancers, and its co-expression with RAGE correlates with cancer metastasis." (PMID 31905926, 2019).
cancer (continued). "To further confirm that HIF-1α is required for the recruitment of YAP, we assessed if HMGB1 promoted YAP binding to pluripotent genes promoter regions by CHIP in HIF-1α knockdown and control CD133− cancer cells." (PMID 31558702, 2019). "Since HMGB1 is thought to bind to CDDP-binding DNA and repair DNA damage, suppressing HMGB1 was thought to reduce the ability of cancer cells to repair DNA and suppress CDDP resistance." (PMID 31905926, 2019). "While ATP, CRT, and HMGB1 represent the classical hallmarks of immunogenic cell death, other molecules behave as DAMPs, for instance annexin A1 (ANXA1) and cancer cell-derived nucleic acid." (PMID 31440242, 2019). "Co-IP assay further confirmed the interaction between HMGB1 and TLR2 when CD133− cancer cells were cocultured with the 250 ng/ml rhHMGB1." (PMID 31558702, 2019). "Several members of the S100 family, specifically S100A8, S100A9, and S100A12, are released from dying cancer cells and appear to contribute to ICD via binding to RAGE for HMGB1." (PMID 30813267, 2019). "We showed that the wild-type WR strain and genetically-engineered vSP induced both necrosis and apoptosis, resulting in the release of high mobility group box 1 (HMGB1) from infected and dying cancer cells." (PMID 30626434, 2019). "Thus, targeting HMGB1-mediated autophagy might improve the chemosensitivity of cancer cells." (PMID 31664305, 2019). "These cancer cells induced by PDT using the novel photosensitizers (i.e., PS and PD) induced emission of the crucial DAMPs such as CRT, HMGB1 and ATP." (PMID 31842994, 2019). "Mouse immunization experiments using cancer cells pretreated with chemotherapeutic drugs, such as doxorubicin or mitoxantrone, have shown effective cancer regression through CRT expression and HMGB1 secretion." (PMID 30498512, 2018). "In two separate studies, TLR2 was reported to mediate HMGB1-induced cytokine production in human embroynic kidney (HEK) cells overexpressing TLR2 and cancer stem cells." (PMID 30134807, 2018). "High-mobility group box 1 (HMGB1) is a major ligand both inducing expression and binding to RAGE, playing a major role in cancer development." (PMID 29529089, 2018). "Previous animal experiments have suggested that release of the nuclear protein HMGB1 into the blood, which affects the metabolism of distant organs, accounts in part for the altered PFAA levels in cancer patients." (PMID 29466971, 2018). "Nonetheless, both CXCL12 and HMGB1 are key players in the TME, where they orchestrate a variety of functions that sustain cancer progression." (PMID 30319638, 2018). "The dendritic cells (DCs) then recognize CRT, HMGB1, and ATP through CD91, Toll-like receptor 4, and P2X purinoreceptor 7, respectively, and take up the cancer cells." (PMID 30498512, 2018). "This suggests that paracrine production of HMGB1 by inflammatory cells mediates its major effect through RAGE expression, again supporting the important role of the HMGB1/RAGE axis in cancer." (PMID 29529089, 2018). "Extracellular HMGB1 promoted ERK activation-induced Drp1 phosphorylation via RAGE, which induced autophagy and acted upon surviving cancer cells to promote regrowth." (PMID 30258050, 2018). "Released HMGB1 has been reported to bind with the receptor for advanced glycation end products (RAGE), promoting autophagy and inhibiting apoptosis in stressed cancer cells." (PMID 29567990, 2018). "The classical HMGB1-RAGE signalling axis and HMGB1-TLR4 pathways have been suggested to play important roles in cancer." (PMID 29246127, 2017). "Our results indicated that miR-200c attenuated cancer EMT, invasion, and migration through decreasing HMGB1 expression." (PMID 28727734, 2017). "High-mobility group box 1 (HMGB1) functions as a proinflammatory cytokine and is one of the most intriguing molecules in inflammatory disorders and cancers." (PMID 28348451, 2017).
cancer (continued). "A previous study also indicated that HMGB1 was highly expressed in RCC, and the expression level showed a positive correlation with cancer bearing, metastasis, and clinical staging and grading." (PMID 28968989, 2017). "HMGB1 has been reported to mediate MMP2 and MMP9 expression in some inflammatory disorders and cancers." (PMID 28348451, 2017). "It is well established that exogenous HMGB1 induces MEK/ERK activation in immune and cancer cells including leukemic cells." (PMID 28404891, 2017). "Notably, even the “danger signals”, such as high-mobility group box 1 protein (HMGB1), can actually support cancer growth through stimulation of myeloid-derived suppressor cells (MDSCs) or nurse-like cells that create conditions favorable for cancer progression." (PMID 28361232, 2017). "CCL2, a member of C-C chemokine family, is known as a major cytokine for the recruitment of myeloid cells including MDSCs from the bone marrow to cancer tissues, and induction of CCL2 in various cells by HMGB1 has also been reported." (PMID 28536706, 2017). "As a downstream signaling pathway activated by extracellular HMGB1, MAPK pathways are related to the progression of several cancers and play an important role in cancer cell growth and malignant transformation." (PMID 26840258, 2016). "Pooled hazard ratios (HRs) and 95% confidence intervals (CIs) were calculated to evaluate the influence of HMGB1 expression on overall survival (OS) and progression-free survival (PFS) in cancer patients." (PMID 27391431, 2016). "The release of nuclear DAMPs, including high mobility group box 1 (HMGB1), histones, and DNA, link genomic instability and inflammation, two of the hallmarks of cancer." (PMID 27623211, 2016). "MIAPaCa-2 cancer cells showed increased VEGF levels after initial TLR ligation either with ODN or LTA alone or combined with ODN and HMGB1 (ODN: 127%, p < 0.05; LTA: 117%, p < 0.05, and ODN + HMGB1: 143%, p < 0.005)." (PMID 27941651, 2016). "Treatment of BxPC-3 cancer cells with LTA alone or in combination with HMGB1 resulted in an increased phosphorylation of Akt (LTA: ROD = 124%; LTA + HMGB1: ROD = 105%)." (PMID 27941651, 2016). "After 48 h of initial stimulation PaCaDD135 cancer cells continued to respond with high PDGF levels (HMGB1: 1768%, p < 0.0001 and ODN + HMGB1: 1119%, p < 0.005)." (PMID 27941651, 2016). "MIAPaCa-2 cells treated with the TLR ligands demonstrated comparably more pronounced pErk activation then BxPC-3 cancer cells (ODN: ROD = 357%, LTA: 295%, LPS: 135%, HMGB1: 296%, ODN + HMGB1: 242%, LTA + HMGB1: 329%, and LPS + HMGB1: 282%)." (PMID 27941651, 2016). "Increased VEGF levels were also observed in PaCaDD135 cancer cells 24 h after treatment with the TLR ligands (ODN: 244%, p < 0.05 and ODN + HMGB1: 140%) (left)." (PMID 27941651, 2016). "PaCaDD135 cells expressed increased Bcl-xL in a range between the other two analyzed cancer cell lines (ODN ROD = 141%, LTA: 142%, LPS: 124%, HMGB1: 113%, ODN + HMGB1: 133%, and LPS + HMGB1: 110%) (right)." (PMID 27941651, 2016). "Thus, HMGB1 stored in secretory granules of NK cells could be an important cytotoxic compound of the innate immune system, affecting the energy metabolism of diverse pathogens and particularly of cancer cells through inhibition of tetrameric PK M2." (PMID 26948869, 2016). "However, HMGB1 was not previously linked with direct cytotoxicity toward cancer cells." (PMID 27652323, 2016). "However, HMGB1 may also have direct deleterious effects on anti-cancer therapy." (PMID 26486085, 2015). "In other settings, however, circulating HMGB1 and RAGE levels appear to reflect well the death of cancer cells exposed to immunogenic treatment modalities." (PMID 26300886, 2015).